ZNF840P (zinc finger protein 840, pseudogene)
Description:
May be involved in transcriptional regulation.
Synonyms: dJ981L23.3; formerly C20orf157; ZNF840
Gene: Protein-coding gene on chromosome 20 (46,459,441 to 46,495,558, forward strand). Ensembl gene ENSG00000184617.
Subcellular location: Nucleus
Homologues: Orthologues: tropical clawed frog znf160 (17% identical). Paralogues in human: ZNF33B (32% identical), ZNF573 (32% identical), ZNF658 (32% identical), ZNF841 (32% identical), ZNF568 (32% identical), ZNF33A (32% identical), ZNF585B (31% identical), ZNF546 (31% identical), ZNF540 (31% identical), ZNF606 (31% identical), ZNF836 (31% identical), ZNF28 (31% identical), and 164 more.